EZH2 (enhancer of zeste 2 polycomb repressive complex 2 subunit)
Diseases named in the same sentence as EZH2 in open-access papers (continued):
Sharing a sentence is not in itself a finding about the gene and the disease.
prostate carcinoma (continued). "Prior studies indicated that at least three separate mechanisms could result in EZH2 upregulation in prostate cancer." (PMID 21941025, 2011). "As such, Myc may contribute to EZH2 elevation in prostate cancer, by directly activating EZH2 transcription, and by repressing its negative regulators, miR-26a and miR-26b." (PMID 21941025, 2011). "EZH2 can modulate the expression of numerous regulatory networks, and there is significant enrichment for EZH2-mediated H3K27me3 polycomb repression signatures in embryonic stem cells, embryonic fibroblasts and advanced prostate cancer." (PMID 21941025, 2011). "EZH2, a polycomb protein, is overexpressed in prostate cancer development." (PMID 24213111, 2011). "Further, in human prostate cancer cells, Myc negatively regulates miR-26a and miR-26b via direct binding to their parental Pol II gene promoters, and forced overexpression of miR-26a and miR-26b in prostate cancer cells results in decreased EZH2 levels and suppressed proliferation." (PMID 21941025, 2011). "In addition to prostate cancer, we have demonstrated that EZH2 protein levels were strongly correlated with breast cancer aggressiveness and promote neoplastic transformation of breast epithelial cells." (PMID 16880794, 2006). "In bone metastatic breast and prostate cancer, enhanced activity of the histone methyltransferase enhancer of zeste 2 (EZH2) reprogrammes disseminated cells into a more stem-like phenotype, and elevates their capacity to seed other sites in mice, which can be prevented with an EZH2 inhibitor." (PMID 41091336, 2025). "Similarly, targeting EZH2 can modulate the resistance of prostate cancer cells to docetaxel." (PMID 40028035, 2025). "Notably, Tazemetostat, an oral EZH2 inhibitor, has demonstrated favorable tolerability in older patients with advanced solid tumors, including those with genitourinary malignancies (e.g., prostate cancer)." (PMID 40918525, 2025). "Androgen receptor (AR) suppresses DPYSL5, and overexpression of DPYSL5 promotes prostate cancer cell plasticity via EZH2-mediated PRC2 activation, suggesting that the AR/DPYSL5/EZH2/PRC2 axis may act as a driver of treatment-induced neuroendocrine prostate cancer." (PMID 38238517, 2024). "USP7 could also deubiquitinate and stabilize EZH2 in prostate cancer cells." (PMID 36878903, 2023). "Thus, we aimed to investigate whether depletion of SNHG4, RRM2, EZH2, AURKA or TK1 can cause prostate cancer cell senescence and affect cell viability." (PMID 37596700, 2023). "Indeed, mice carrying Treg-specific Ezh2 deficiency showed a reduced growth of different types of tumors (e.g., CRC, melanoma, prostate cancer) in association with the reprograming of tumor-infiltrating Tregs in anti-tumor effector cells (e.g., IL-2, IFNγ, and TNF)." (PMID 36900330, 2023). "However, the deletion of EZH2 inhibited the growth of prostate cancer cells." (PMID 36672374, 2023). "There are also many potent and more bioavailable EZH2 catalytic inhibitors currently undergoing phase 1/2/3 clinical trials, alone or in combination with other drugs, for the treatment of several solid tumors, mainly lymphoma, prostate cancer, and small cell lung cancer." (PMID 36076977, 2022). "Studies also found frequent mutations in the EZH2 SET domain [for example, tyrosine residue 646 (Y646)] and EZH2 somatic mutations in various tumors such as germinal center (GC) diffuse large B-cell lymphoma (DLBCL), non-small cell lung cancer, prostate cancer, and colon carcinoma." (PMID 34604069, 2021).
prostate carcinoma (continued). "EZH2 also showed surprising results in reversing the chemotherapy resistance of cervical cancer cells, cisplatin resistance in epithelial ovarian cancer, melanoma resistance to immunotherapy, and resistance of prostate cancer, and it can be described as the gospel for patients." (PMID 34149432, 2021). "EZH2 knockdown in all three cancer types and small molecule inhibition in the docetaxel-resistant prostate cancer potentiated cancer cell sensitivity to the chemotherapy agents, suggesting that EZH2 inhibition in combination with FLOT chemotherapy could improve treatment sensitivity in OAC." (PMID 34439236, 2021). "Besides that, EZH2 expression is positively correlated with MYC expression in prostate cancer." (PMID 33014831, 2020). "A previous study has shown that EZH2 may function upstream of NSD2 in prostate cancer." (PMID 33665162, 2020). "We previously reported the deubiquitinatingactivity of USP44 and subsequent EZH2 protein stabilization in prostate cancer cellsand suggested that targeting USP44 might be an efficient anticancer strategy forEZH2-dependent cancers irrespective of the enzymatic activity of EZH2." (PMID 32453339, 2020). "Importantly, inhibition of EZH2 could significantly suppress prostate cancer cell proliferation and invasion in vivo and in vitro, supporting EZH2 as a promising therapeutic target." (PMID 31636385, 2020). "Thus, our results provide for the first line evidence of EZH2-mediated repression of HNF1B during prostate cancer progression, which may also exist in other cancer types." (PMID 31636385, 2020). "Furthermore, the genome-wide analysis of various datasets of primary and metastatic prostate cancers showed that the concurrent EZH2 and TOP2A expression identifies a number of patients with more aggressive disease and overlap with genes involved in mitotic regulation." (PMID 31366128, 2019). "Interestingly, any of these two events was sufficient to promote the formation of prostate cancer, but only the functional synergy of the oncogenic function of AR and KRAS signaling could promote prostate cancer progenitors in vivo and elevate EZH2 expression." (PMID 31366128, 2019). "Indeed, ISO treatment in prostate cancer cells induces angiogenesis tube formation of SVEC4-10 endothelial cells, which is reversed either by treating prostate cancer cells with EZH2 inhibitor GSK126 or EPZ6438, or by adding TSP1 peptide to the conditioned medium of cancer cells." (PMID 30287808, 2018). "Likewise, cytoplasmic EZH2 expression has been observed in prostate cancer cells." (PMID 30022044, 2018). "We first examined whether TSP1 is indeed an EZH2 target in prostate cancer cells." (PMID 30287808, 2018). "Several studies have shown that the Polycomb repressive complex 2 (PRC2) subunit EZH2 and DNMT3a can cooperate for transcriptional repression; while the interaction between AR and EZH2 has recently been shown to be important for regulating genes in prostate cancer development." (PMID 29383141, 2017). "AKT1-mediated phosphorylation of EZH2 allows its interaction with androgen receptor promoting the expression of androgen receptor-target genes in the absence of androgens further supporting the involvement of EZH2 in the development and progression of castrate resistant prostate cancer." (PMID 27793053, 2016). "It should be noted though that EZH2 activity has also been associated with transcriptional activation of oncogenic signaling pathways associated with CSC survival and proliferation such as Wnt signaling in colorectal cancer, NOTCH1 and TGFβ1 in prostate cancer, and STAT3 pathway in glioblastoma." (PMID 27793053, 2016). "Thus, we consider RUNX1 as a target of EZH2 in prostate cancer." (PMID 25537508, 2015).
prostate carcinoma (continued). "Notably, the auxiliary protein Uhrf1 found in the ‘darkorange’ module has previously been shown to interact with PRC2 members Ezh2 and Suz12 in prostate cancer cells, where elevated UHRF1 levels correlate positively with an increase in EZH2 and were associated with poor clinical outcome." (PMID 25605797, 2015). "Besides, that could be more important, the reduced expression of DAB21P correlated with the increased expression of the transcriptional repressor EZH2, which proved to be one of the strongest markers of aggressive prostate cancer." (PMID 27351008, 2014). "Moreover, EZH2 expression is up-regulated in various cancers and has been found to serve as a marker of the aggressive stages and clinical behavior of bladder and prostate cancers." (PMID 25431950, 2014). "Prior to the present study, three molecular mechanisms were identified that could be responsible for overexpression of EZH2 in prostate cancer--amplification of the EZH2 gene, the deletion of its negative regulator miR-101, and transcriptional regulation of EZH2 by ETS gene family members." (PMID 21941025, 2011). "To address whether EZH2 is a direct target of transcriptional activation by Myc in prostate cancer, we carried out chromatin immunoprecipitation (ChIP), and enriched Myc binding approximately 1kb and 2kb upstream of the transcription start site of EZH2, which contains a canonical E-box." (PMID 21941025, 2011). "Thus, we hypothesized that additional mechanisms are likely operative that induce EZH2 upregulation in prostate cancer, at least during the early phases of the disease." (PMID 21941025, 2011). "Hence, these results support the concept that EZH2 may be an early contributor to prostate cancer development, in addition to being a potent driver of the progression to aggressive, metastatic disease." (PMID 21941025, 2011). "However, the molecular mechanisms by which EZH2 contributes to prostate cancer initiation and progression as well as the factors controlling its expression in this context remain largely unknown." (PMID 20479932, 2010). "In addition, in prostate cancer cells, EZH2 was found to promote invasiveness and proliferation." (PMID 19773751, 2009). "The Polycomb Group protein, EZH2, is over-expressed in hormone-refractory and metastatic prostate cancer and may play a role in the progression of prostate cancer as well as serve as a marker distinguishing indolent prostate cancer from those at risk of lethal progression." (PMID 17125514, 2006). "Here, we discover the well-known histone lysine methyltransferase enhancer of zeste homologue 2 (EZH2) as an unexplored ADAR interactor and editing regulator in prostate cancer (PCa)." (PMID 41882000, 2026). "Treatment of human prostate cancer cell lines DU145 and 22Rv1, known for high constitutive EZH2 expression, with luteolin significantly reduced EZH2 and suppressor of zeste 12 (SUZ12) protein levels in a dose- and time-dependent manner." (PMID 41226811, 2025). "Since EZH2 enables cells to acquire invasive traits, SETD2-mediated EZH2-K735me1 is functionally and clinically important to restrict prostate cancer metastasis." (PMID 40746737, 2025). "Epigenetic modifications play a crucial role in regulating prostate cancer progression, particularly involving histone methyltransferases such as SET-domain containing 2 (SETD2) and Enhancer of Zeste homolog 2 (EZH2)." (PMID 40959108, 2025). "The co-expression of DNMT1 and the Enhancer of zeste homolog 2 (EZH2), alongside their correlation with poor prognostic markers in prostate cancer, underscores the importance of DNMT1 in maintaining tumor-promoting epigenetic landscapes." (PMID 40034825, 2025). "Silibinin treatment of DU145 and PC3 prostate cancer cell lines resulted in a significant reduction in the expression of PRC2 complex members, including EZH2, SUZ12, and EED." (PMID 41226811, 2025).
prostate carcinoma (continued). "Mechanistically, AR inhibits TDO2 transcription by binding to the TDO2 intron and suppresses GR expression; simultaneously, EZH2-mediated H3K27me3 on the TDO2 transposon (L1PA5) blocks GR binding and TDO2 transcription in androgen-sensitive prostate cancer." (PMID 40759641, 2025). "In the context of prostate cancer, SETD2 directly methylates enhancer of zeste homolog 2 (EZH2) at K735 to facilitate its degradation." (PMID 40746737, 2025). "Enhancer of zeste homolog 2 (EZH2), a histone methyltransferase and key component of the Polycomb repressive complex 2 (PRC2), is frequently overexpressed in prostate cancer and contributes to tumor progression." (PMID 41154392, 2025). "Our X2K analysis unveiled heightened expression of EZH2 and SUZ12, core components of the PRC2 complex, in AA prostate cancer." (PMID 40104216, 2025). "Therefore, epigenetic therapies targeting pathways such as EZH2 could be explored, given the loss of the transcriptional repressor REST in both AMPC and NEPC, indicating a potential role for epigenetic dysregulation in these prostate cancers." (PMID 39349591, 2024). "One of these compounds is the histone H3K27 methyltransferase EZH2 inhibitor DZNeP, which we previously identified as a candidate that targets ALDH+ CSCs in prostate cancer." (PMID 38398123, 2024). "In this regard, five mRNAs (CCND1, LMTK2, FN1, EZH2, and GOLM1) were included in a gene panel for prostate cancer diagnosis and reported as differentially expressed in a Chinese cohort of 281 patients using RT-qPCR from tissue samples." (PMID 39595075, 2024). "THBS1 was found to be a direct target of epigenetic suppression by the enhancer of zeste homolog 2 (EZH2), which can directly regulate THBS1, thereby promoting neuroendocrine progression and angiogenesis in invasive prostate cancer." (PMID 39273281, 2024). "In conclusion, DPYSL5 plays a critical role in regulating prostate cancer cell plasticity, and we propose the AR/DPYSL5/EZH2/PRC2 axis as a driver of t-NEPC progression." (PMID 38238517, 2024). "To better understand the mechanisms of NED in prostate cancer cells, here we investigated the links between ADT, CREB1, EZH2, and REST." (PMID 38777812, 2024). "Transcription factors such as Myc in prostate cancer cells and the EWS-FLI1 fusion protein in Ewing sarcoma cells can bind to the EZH2 promoter and enhance its expression." (PMID 38886296, 2024). "It remains an interesting question for future investigation regarding how the EZH2-REST relationship evolves during prostate cancer progression, from REST being an EZH2 partner in prostate adenocarcinoma cells to REST becoming an EZH2 target in NEPC cells." (PMID 38777812, 2024). "A comparison of other major EMT markers between PC3 and PC-3M revealed EZH2, Snail/SNAI1, Slug/SNAI2, and TWIST1, were expressed highly in PC-3M compared with PC-3, yet both are ARLow/mCRPC/NEPC prostate cancer subtypes." (PMID 37476073, 2023). "In prostate cancer, ATAD2 can bind to the promoter of EZH2 together with KDM8 and E2F1 to promote the transcription of EZH2." (PMID 36632213, 2023). "Similar to prostate cancer cells and derived PDOs, early PCCs and PDOs derived from them expressed cancer markers AMACR, TMPRSS2-ERG, and EZH2." (PMID 36769153, 2023). "In prostate cancer, BAZ2A (TIP5) was found overexpressed and interacting with EZH2 to maintain silenced anti-metastatic genes." (PMID 37369946, 2023). "Previous studies have identified dual upregulation of EZH2 and TOP2A as biomarkers for early identification of increased metastatic potential and recurrence among patients undergoing radiotherapy for prostate cancer." (PMID 38008711, 2023). "To investigate the biochemical and biological consequences of EZH2 and HDAC inhibitors in prostate cancer, we used a panel of cell lines including PC3 (AR-), C42B (AR independent), LnCAP (AR dependent), and PT-09 cells (mouse, AR independent)." (PMID 37104245, 2023).
prostate carcinoma (continued). "Metformin has been shown to combat EZH2-high prostate cancer by stimulating SETD2, which regulates EZH2-K735me1 to induce EZH2 destruction, thereby inhibiting prostate cancer metastasis." (PMID 37344841, 2023). "By connecting metabolic and epigenetic changes, SET domain-containing 2 (SETD2), a histone lysine methyltransferase, integrates enhancer of zeste homolog 2 (EZH2) and the AMPK signaling pathway to limit prostate cancer spread." (PMID 36831413, 2023). "Some of these proteins including AR, SMAD, NANOG, EZH2, and KLF have demonstrated prognostic significance in advance-stage prostate cancer." (PMID 36672280, 2023). "We assumed that SNHG4 facilitates prostate cancer cell proliferation, the cell cycle and senescence by regulating RRM2, EZH2, AURKA and TK1." (PMID 37596700, 2023). "Epigenetic, transcriptional, and functional studies show that two major epigenetic regulators (EZH2 and HDAC) buffer advanced prostate cancer from lethal stress responses, revealing a promising combination therapy for castration-resistant disease." (PMID 37104245, 2023). "In contrast, late PCCs lost expression of epithelial markers, although PCCs prepared from PCaT continued to express androgen receptor (AR1) and prostate cancer markers AMACR and EZH2." (PMID 36769153, 2023). "More importantly, we have discovered that EZH2 and HDAC inhibitors kill prostate cancers, in part, by activating a broad stress response gene, which is normally repressed in advanced tumors." (PMID 37104245, 2023). "Enhancer of zeste homolog 2 (EZH2) directly targets THBS1, thus promoting neuroendocrine progression and angiogenesis in aggressive prostate cancer." (PMID 38203613, 2023). "The expression of EZH2 and G9a was also higher in highly metastatic colon cancer cells (HCT116) or prostate cancer cells (DU145) than in SW480 and PC3 cells (B right)." (PMID 35409271, 2022). "In prostate cancer cells, GTP/EGCG therapy significantly reduced class I HDAC activity/expression, as well as EZH2 and H3K27me3 levels." (PMID 35327559, 2022). "studies have shown that lncRNAs indirectly affect autophagy in prostate cancer via regulating other molecular pathways such as PARP, PI3K-AKT-MTOR, and EZH2." (PMID 35317831, 2022). "SETD2 (SET domain-containing 2, a histone lysine methyltransferase) integrates EZH2 (enhancer of zeste homolog 2) and the AMPK signaling pathway to restrict prostate cancer metastasis by linking metabolism with epigenetic modifications." (PMID 34050894, 2022). "In turn, EZH2 as an upstream mediator, down-regulates miRNA-200c expression to induce E2F3-mediated cell cycle progression in prostate cancer." (PMID 35236381, 2022). "In support of this concept, a recent study found that inhibition of EZH2 activated a dsRNA–STING–IFN stress response that increased intratumoral trafficking of activated CD8+ T cells and sensitized prostate cancer cells to PD-1 checkpoint blockade." (PMID 36923279, 2022). "Apparently, hypoxia induced the expression of the enhancer of zeste homolog 2 (EZH2), a histone methyltransferase, which in turn regulates the hypermethylation of the TGFBR2 promoter in a model of prostate cancer." (PMID 35565420, 2022). "Epigenetic repression of EAF2-HIF1α by EZH2 has been shown to foster metabolic reprogramming in glioblastoma and to promote aerobic glycolysis by upregulating HK2 in prostate cancer." (PMID 35888776, 2022). "USP7 can coordinate with histone-lysine N-methyltransferase EZH2 (EZH2)-catalyzed methylation to remove ubiquitination and enhance FOXA1 protein stability, promoting prostate cancer growth." (PMID 35414786, 2022). "Effects of miR-101 on EZH2 have been observed in various cancers, and downregulation of this microRNA and elevation of EZH2 have been found in NSCLC tumor tissues, prostate cancer, and renal cancer." (PMID 35087589, 2022).